AMBRA1 (autophagy and beclin 1 regulator 1)
Description:
Substrate-recognition component of a DCX (DDB1-CUL4-X-box) E3 ubiquitin-protein ligase complex involved in cell cycle control and autophagy. The DCX(AMBRA1) complex specifically mediates the polyubiquitination of target proteins such as BECN1, CCND1, CCND2, CCND3, ELOC and ULK1. Acts as an upstream master regulator of the transition from G1 to S cell phase: AMBRA1 specifically recognizes and binds phosphorylated cyclin-D (CCND1, CCND2 and CCND3), leading to cyclin-D ubiquitination by the DCX(AMBRA1) complex and subsequent degradation. By controlling the transition from G1 to S phase and cyclin-D degradation, AMBRA1 acts as a tumor suppressor that promotes genomic integrity during DNA replication and counteracts developmental abnormalities and tumor growth. AMBRA1 also regulates the cell cycle by promoting MYC dephosphorylation and degradation independently of the DCX(AMBRA1) complex: acts via interaction with the catalytic subunit of protein phosphatase 2A (PPP2CA), which enhances interaction between PPP2CA and MYC, leading to MYC dephosphorylation and degradation. Acts as a regulator of Cul5-RING (CRL5) E3 ubiquitin-protein ligase complexes by mediating ubiquitination and degradation of Elongin-C (ELOC) component of CRL5 complexes. Acts as a key regulator of autophagy by modulating the BECN1-PIK3C3 complex: controls protein turnover during neuronal development, and regulates normal cell survival and proliferation. In normal conditions, AMBRA1 is tethered to the cytoskeleton via interaction with dyneins DYNLL1 and DYNLL2. Upon autophagy induction, AMBRA1 is released from the cytoskeletal docking site to induce autophagosome nucleation by mediating ubiquitination of proteins involved in autophagy. The DCX(AMBRA1) complex mediates 'Lys-63'-linked ubiquitination of BECN1, increasing the association between BECN1 and PIK3C3 to promote PIK3C3 activity (By similarity). In collaboration with TRAF6, AMBRA1 mediates 'Lys-63'-linked ubiquitination of ULK1 following autophagy induction, promoting ULK1 stability and kinase activity. Also activates ULK1 via interaction with TRIM32: TRIM32 stimulates ULK1 through unanchored 'Lys-63'-linked polyubiquitin chains. Also acts as an activator of mitophagy via interaction with PRKN and LC3 proteins (MAP1LC3A, MAP1LC3B or MAP1LC3C); possibly by bringing damaged mitochondria onto autophagosomes. Also activates mitophagy by acting as a cofactor for HUWE1; acts by promoting HUWE1-mediated ubiquitination of MFN2. AMBRA1 is also involved in regulatory T-cells (Treg) differentiation by promoting FOXO3 dephosphorylation independently of the DCX(AMBRA1) complex: acts via interaction with PPP2CA, which enhances interaction between PPP2CA and FOXO3, leading to FOXO3 dephosphorylation and stabilization. May act as a regulator of intracellular trafficking, regulating the localization of active PTK2/FAK and SRC (By similarity). Also involved in transcription regulation by acting as a scaffold for protein complexes at chromatin (By similarity).
Synonyms: DCAF3; KIAA1736; FLJ20294; WDR94
Tractability: PROTAC: UniProt records ubiquitination sites on it; ubiquitination databases record sites on it; its protein half-life has been measured.
Gene: Protein-coding gene on chromosome 11 (46,396,414 to 46,594,125, reverse strand). Ensembl gene ENSG00000110497.
Subcellular location: Endoplasmic reticulum; Cytoplasm, cytoskeleton; Cytoplasmic vesicle, autophagosome; Mitochondrion; Cytoplasm, cytosol; Nucleus; Cell junction, focal adhesion
Subcellular location (Human Protein Atlas): Vesicles; Mitochondria
Pathways (Reactome):
Autophagy: Macroautophagy
Gene Ontology:
Molecular function: GTPase binding; protein binding; protein phosphatase activator activity; protein phosphatase binding; ubiquitin protein ligase binding; ubiquitin-like ligase-substrate adaptor activity
Biological process: autophagosome assembly; mitophagy; positive regulation of autophagy; positive regulation of free ubiquitin chain polymerization; positive regulation of mitophagy; positive regulation of phosphatidylinositol 3-kinase/protein kinase B signal transduction; positive regulation of regulatory T cell differentiation; proteasome-mediated ubiquitin-dependent protein catabolic process; protein polyubiquitination; regulation of G1/S transition of mitotic cell cycle; response to mitochondrial depolarisation; regulation of cell cycle phase transition; autophagy; cellular response to starvation; negative regulation of cardiac muscle cell apoptotic process; protein ubiquitination; regulation of transcription by RNA polymerase II; response to nutrient levels
Cellular component: Cul4-RING E3 ubiquitin ligase complex; cytoplasm; cytoskeleton; cytosol; endoplasmic reticulum; mitochondrion; nucleus; axoneme; Cul4A-RING E3 ubiquitin ligase complex; Cul4B-RING E3 ubiquitin ligase complex; mitochondrial outer membrane; perinuclear region of cytoplasm; autophagosome; focal adhesion; phagocytic vesicle
Genetic constraint (gnomAD): Loss-of-function variants: 46 observed, 119.9 expected, observed/expected ratio (o/e) 0.38, 90% interval 0.3 to 0.49. The upper end of that interval is the gene's LOEUF score, 0.49, which puts it in group 2 of 6, group 1 being the genes least tolerant of losing a copy. Missense variants: 1,327 observed, 1,718 expected, observed/expected ratio (o/e) 0.77, 90% interval 0.74 to 0.81. Synonymous variants: 626 observed, 666.9 expected, observed/expected ratio (o/e) 0.94, 90% interval 0.88 to 1.
Homologues: Orthologues: chimpanzee AMBRA1 (99% identical), pig AMBRA1 (97% identical), rabbit AMBRA1 (97% identical), rat Ambra1 (96% identical), mouse Ambra1 (96% identical), guinea pig AMBRA1 (95% identical), macaque AMBRA1 (94% identical), dog AMBRA1 (94% identical), tropical clawed frog ambra1 (73% identical), zebrafish ambra1b (60% identical), zebrafish ambra1a (57% identical).
Diseases named in the same sentence as AMBRA1 in open-access papers:
AMBRA1 is named in the same sentence as 98 diseases in open-access papers, as found by Europe PMC text mining. Sharing a sentence is not in itself a finding about the gene and the disease. The quoted sentences say what the papers report.
melanoma (19 papers, 2016 to 2026). A malignant, usually aggressive tumor composed of atypical, neoplastic melanocytes. "Ultimately, we conclude that AMBRA1 loss upregulates metastatic genes/proteins highlighting AMBRA1 as a tumor suppressor gene in melanoma." (PMID 42231548, 2026). "Analysis of TCGA data showed that the highest frequency of AMBRA1 genetic alterations occurred in uterine corpus endometrial carcinoma, melanoma, and STAD, with missense mutations being the primary alteration type." (PMID 39720719, 2024). "In melanoma, Ambra1 deficiency accelerated tumor growth and reduced overall survival in a Braf/Pten mutant mouse model of melanoma." (PMID 37225761, 2023). "By these means, we classified mutations of AMBRA1 in melanoma, where AMBRA1 is highly mutated and displays a tumor-suppressive role." (PMID 36243772, 2022). "Collectively, these data suggest a paracrine mechanism whereby TGF‐β2 causes loss of AMBRA1 overlying high‐risk AJCC early‐stage melanomas and reduced epidermal integrity, thereby facilitating erosion of the epidermis and tumour ulceration." (PMID 34773645, 2022). "In summary, these data suggest a paracrine mechanism whereby melanoma secretion of TGF‐β2 causes peritumoral loss of AMBRA1 and reduced epidermal integrity facilitating erosion of the epidermis and tumour ulceration." (PMID 34773645, 2022). "The aim of the present study was to evaluate the potential contribution of melanoma paracrine transforming growth factor (TGF)‐β signalling to the loss of AMBRA1 in the epidermis overlying the primary tumour and disruption of epidermal integrity." (PMID 34773645, 2022). "In this contribution we have tested our approach on the protein AMBRA1, focusing on cancer mutations from melanoma." (PMID 36243772, 2022). "Due to its structure, propensity to interact with other proteins, and cancer-related functions, we sought to apply Cancermuts to AMBRA1 in order to predict the pathogenicity of its mutations in melanoma." (PMID 36243772, 2022). "Then, we found that the ablation of AMBRA1 promoted the proliferation of 92.1 and OMM1 cells, which was somehow consistent with recently reported that loss of AMBRA1 promotes melanoma growth and invasion." (PMID 34901460, 2022). "Here the authors show that Ambra1 deficiency accelerates melanoma growth and increases metastasis in mouse models of melanoma through FAK1 hyperactivation." (PMID 33953176, 2021). "In order to address the relevance of these findings in vivo, we analyzed the ability of Ambra1-deficient melanoma cells to colonize other organs." (PMID 33953176, 2021). "On the other hand, we demonstrated that the pharmacological inhibition of FAK1 signaling was sufficient to revert the growth of Ambra1-deficient Braf/Pten-driven melanomas in vivo." (PMID 33953176, 2021). "Consistently, we have shown that Ambra1 loss deeply affects the melanoma microenvironment, marked by the upregulation of ECM-related genes, such as Mmps and lysyl-oxidases (Loxl)." (PMID 33953176, 2021). "AMBRA1 deficiency in mouse models increases the risk to develop melanoma, significantly enhances melanoma onset, cell proliferation, invasion, and metastasis compared to AMBRA1 WT." (PMID 34830777, 2021). "As for this aspect, we have provided evidence that AMBRA1-deficient melanoma cells efficiently degrade gelatin matrix, thus pointing to their direct involvement in ECM remodeling." (PMID 33953176, 2021). "The more invasive state of Ambra1-deficient tumors was accompanied by other key processes specific to high-invasive melanomas, such as ECM proteolysis/remodeling, EMT activation and FA activation." (PMID 33953176, 2021). "This additional evidence is in agreement with results provided elsewhere, and indicates that loss of Ambra1 likely promotes melanoma growth by increasing cell proliferation." (PMID 33953176, 2021). "In particular, we found that Ambra1 deficiency accelerates tumor growth and leads to an earlier invasive and aggressive phenotype of Braf/Pten melanoma." (PMID 33953176, 2021).
melanoma (continued). "Altogether, these results indicate that loss of Ambra1 promotes melanoma invasion by inducing ECM remodeling and an EMT-like phenotype." (PMID 33953176, 2021). "In fact, while autophagy flux was affected in AMBRA1-silenced cells, bulk autophagy was not altered in Ambra1-null Braf-mutated melanocytes and melanomas, thus implying compensatory events taking place in the tumor." (PMID 33953176, 2021). "Of the highest importance, our data clearly show that loss of Ambra1 not only accelerates the tumor growth, but also promotes the invasive state of melanoma." (PMID 33953176, 2021). "Conversely, loss of AMBRA1 in the epidermis overlying primary melanomas defines a novel prognostic biomarker for AJCC stage I tumors." (PMID 27882308, 2016). "The loss of peritumoral AMBRA1 identifies AJCC Stage I melanomas with high metastatic risk." (PMID 39201498, 2024). "For patients with early American Joint Committee on Cancer (AJCC)‐stage melanoma the combined loss of the autophagy regulatory protein AMBRA1 and the terminal differentiation marker loricrin in the peritumoral epidermis is associated with a significantly increased risk of metastasis." (PMID 34773645, 2022). "Indeed, AMBRA1—when compared to other cancer studies, shows the highest mutation rate in skin cancers, such as melanoma." (PMID 36243772, 2022). "Comprehensively, our results indicate that, although differently, the expression of the AMBRA1 L110F and P170S mutants, predicted to be pathogenic, accelerates the wound closure capacity of melanoma cells and activates the EMT process and the FAK1 oncogenic signaling pathway." (PMID 36243772, 2022). "The aim of this study was to determine whether paracrine TGF‐β signalling results in the loss of AMBRA1 and loricrin (AMLo) levels in the epidermis overlying early‐stage melanomas." (PMID 34773645, 2022). "The loss of epidermal AMBRA1 and loricrin overlying melanoma tumours may therefore define a surrogate marker of incipient melanoma ulceration that identifies a high‐risk subgroup of patients associated with poorer prognosis." (PMID 34773645, 2022). "Indeed, melanoma is one of the cancer types in which AMBRA1 displays a crucial anti-tumorigenic role and a mutational rate among the highest." (PMID 36243772, 2022). "Furthermore, loss of tumoral AMBRA1 can accelerate melanoma growth and metastasis in a BrafV600E/Pten‐deleted mouse model of melanoma." (PMID 34773645, 2022). "Indeed, Ambra1-deficient tumors displayed increased metastatic dissemination to local lymph nodes and increased homing of melanoma cells to the lungs." (PMID 33953176, 2021). "Specifically, we have shown that Ambra1-deficient melanomas are larger and display faster growth kinetics, with reduced overall mice survival, and melanoma cells showing higher capability to affect ECM architecture, migrate and invade, eventually enhancing melanoma metastasis." (PMID 33953176, 2021). "Indeed, we show that Ambra1 deficiency confers accelerated tumor growth and decreased overall survival in Braf/Pten-mutated mouse models of melanoma." (PMID 33953176, 2021). "Recently, it was reported that concomitant loss of AMBRA1 and Loricrin (a major component of cornified cells) expression in the peritumoral epidermis represents a prognostic biomarker for early-stage melanoma and high-risk tumor subsets, independently from tumor invasion depth." (PMID 33953176, 2021). "Indeed, autophagy disruption by AMBRA1 deficiency in melanoma cells was found to be compensated by alternative mechanisms, shedding light on new routes regarding its involvement in cancer." (PMID 34830777, 2021). "This suggests that, at least in the case of melanoma, the pro-invasive phenotype of Ambra1-null cells may associate with tumors in a more de-differentiated state." (PMID 33953176, 2021).
melanoma (continued). "Decreased AMBRA1 expression in the epidermis overlying primary melanomas in a discovery cohort of 76 AJCC stage I tumours was associated with a 7‐year disease‐free survival (DFS) rate of 81·5% vs. 100% survival with maintained AMBRA1 (P < 0·081)." (PMID 31056744, 2020). "In order to understand whether or not FAK1 played a role in the invasive and migratory ability observed upon AMBRA1 deficiency, we performed wound healing and transwell migration assays in siAMBRA1 melanoma cells concomitantly downregulating FAK1 (siAMBRA1:siFAK1 double knocked down)." (PMID 33953176, 2021). "Here, we investigated AMBRA1's involvement in various cellular processes using a systems-based "omics" approach, focusing on melanoma." (PMID 42231548, 2026). "In contrast to its tumor suppressor role in melanoma, our findings revealed that AMBRA1 functions as an oncogene in STAD." (PMID 39720719, 2024). "In melanoma, tumor suppressive activity of AMBRA1 was correlated with oncogenic BRAF signaling, corroborating previous results." (PMID 39617889, 2024). "For instance, while AMBRA1 acts as a tumor suppressor in melanoma, it is overexpressed in several malignancies, including pancreatic ductal adenocarcinoma (PDAC), cholangiocarcinoma (CHOL) and STAD." (PMID 39720719, 2024). "Autophagy regulator AMBRA1 is involved in a variety of biological processes, including autophagy, proliferation and apoptosis, and it exhibits anti-tumor effects in melanoma." (PMID 36830707, 2023). "Our experimental settings consist of transfecting melanoma cells with a siRNA targeting the 5’-UTR region of AMBRA1 (siAMBRA1#2) prior to mutant re-expression." (PMID 36243772, 2022). "We have previously identified loss of AMLo (combined loss of AMBRA1 and loricrin in the epidermis overlying the tumour) as a novel independent prognostic biomarker in early‐stage melanoma and identified a functional role for AMBRA1 in epidermal homeostasis." (PMID 34773645, 2022). "The increased levels of Cyclin D1 and the hyperactivation of FAK1 signaling upon Ambra1 depletion have been previously correlated to boosted proliferative rate and invasiveness of melanoma, respectively." (PMID 36243772, 2022). "We have collected all available melanoma-associated mutations for AMBRA1 from COSMIC and mutations associated with melanoma studies from cBioPortal on 8 April 2020." (PMID 36243772, 2022). "Intriguingly, when we expressed the FAK1P876A/P882A mutant (HA-FAK1.miResAA)—previously reported to abrogate the interaction with AMBRA120— in FAK1 depleted SK-Mel-5 melanoma cells (siFAK1), we observed a reduction in AMBRA1/FAK1 interaction." (PMID 33953176, 2021). "Herein, we provide evidence that the Activating Molecule in Beclin-1-Regulated Autophagy (Ambra1) contributes to melanoma development." (PMID 33953176, 2021). "Along with this, an upregulation of several types of collagen and an altered ECM architecture were observed in Ambra1-null melanomas, thus arguing for a more tumor-permissive environment." (PMID 33953176, 2021). "Overall, these findings suggest that AMBRA1-mediated regulation of FAK1 signaling affects the invasive capacity of melanoma cells and impacts tumor growth in vivo." (PMID 33953176, 2021). "The results herein reported argue for a major role of Ambra1 in the different phases of melanoma development, as demonstrated in the Braf/Pten mouse models of melanoma, which recapitulate key pathophysiological aspects of the human disease." (PMID 33953176, 2021). "WB analyses revealed a marked increase of the phospho-active forms of FAK1 (pFAK-Y397 and -Y576) and SRC (pSRC-Y416) in BPA−/− tumors and in human melanoma cells silenced for AMBRA1, as well as in iLN metastasis of BPA−/− and in melanocytic nevi of BA−/− mice." (PMID 33953176, 2021).